KDR (kinase insert domain receptor)
Diseases named in the same sentence as KDR in open-access papers (continued):
Sharing a sentence is not in itself a finding about the gene and the disease.
tumor (continued). "In this situation, the increased levels of vascular growth factors within the tumor microenvironment can promote tumorigenesis, triggered by FLT4 amplification (encoding VEGFR3) and KDR mutation (encoding VEGFR2)." (PMID 39202050, 2024). "Only patients with KDR positive tumor cells have a shorter disease-free survival compared to those without or with focal and diffuse vascular KDR expression (p = 0.015)." (PMID 39000466, 2024). "Bevacizumab inhibits the binding of VEGF to its receptors, FLT-1 and KDR, on the surface of endothelial cells, resulting in the reduction of tumor vascularization and a subsequent reduction in tumor growth." (PMID 39003252, 2024). "These ligands, especially VEGF-A, bind to receptors such as VEGFR-1 (Flt-1), VEGFR-2 (KDR/Flk-1), and VEGFR-3, along with the coreceptor neuropilins, to induce normal and tumor-associated angiogenesis." (PMID 38498275, 2024). "CSF1R, FGFR1, FLT3, and KDR are related to the tumor microenvironment, and ERBB4, STK11, PTEN, and NPM1 are related to proliferation-related factors." (PMID 36780540, 2023). "Previous studies have shown that VEGF and the high-affinity VEGF receptor KDR are key regulators of tumor angiogenesis." (PMID 37114147, 2023). "The anti-VEGFR treatment Lenvatinib reduced the tumor size of KDR-Var murine tumors (p = 0.0159), and KDR-Var cells showed synergistic cytotoxicity to the combination of dabrafenib and lenvatinib." (PMID 38201446, 2023). "The fact that U87 MG tumours had less pronounced vascular networks in the presence of ASC-EVs provides additional evidence that KDR plays a vital role in tumour vascularization." (PMID 37174646, 2023). "VEGF‐A and its receptors VEGFR‐1 (Flt‐1) and VEGFR‐2 (KDR/Flk‐1) play major roles in physiological as well as pathological tumor angiogenesis." (PMID 37803932, 2023). "Our data revealed that KDR Q472H can alter an anti-tumor immune response as a result of increased angiogenesis." (PMID 38201446, 2023). "A unique observation of our study is the substantial overlap of genes involved in tumor manifestation/association with the genes involved in cardiotoxicity and neurotoxicity such as ESR1, PTGS2, LTA and KDR." (PMID 37069190, 2023). "VEGF is a prime regulator of tumor angiogenesis and vasculogenesis, and KDR is a receptor for various VEGF isoforms." (PMID 37114147, 2023). "Several pharmacological research and clinical studies indicate that the KDR blockage would be a promising strategy to suppress tumor‐induced angiogenesis." (PMID 35313079, 2022). "The previous analysis also showed that PROZ has the highest correlation with the main tumor vascular signals (expression of KDR), and the key to the effectiveness of the combined treatment of HCC with ICIs is to block the VEGF pathway of HCC angiogenesis." (PMID 36140703, 2022). "One such example is the interaction of galectin-1, a secretory galactoside-binding protein induced by hypoxia, with the N-glycan part of KDR on cell surface, thereby conferring VEGF-like signaling for tumor-associated angiogenesis." (PMID 36517806, 2022). "Using our fusion gene database, we identified gene–gene fusions in cfDNA and tumour DNA, such as KDR‐PDGFRA (8%), and NCDN‐PDGFRA (40%) that correspond to the previously reported alterations of PDGFRA in GBM (43% of all our samples)." (PMID 34875133, 2022). "VEGF-A interacts with higher infinity with Flt-1, although KDR induced stronger phosphorylation signaling cascade to induce proliferation, survival, and increase permeability in endothelial or tumor cells." (PMID 35878392, 2022). "VEGFC is the main regulator of angiogenesis and accelerates tumor progression by promoting angiogenesis by binding to the kinase insert domain receptor (VEGFR-2)." (PMID 35587748, 2022).
tumor (continued). "Using our gene–gene fusion database, ChiTaRS 5.0, we identified gene–gene fusions in cfDNA and tumour DNA, such as KDR–PDGFRA and NCDN–PDGFRA, which correspond to previously reported alterations of PDGFRA in GBM (44% of all samples)." (PMID 34875133, 2022). "Vascular endothelial growth factor (VEGF) expression, through the expression of the cell-surface kinase VEGFR-2 (KDR/Flk-1), is strongly associated with both angiogenesis and tumor aggressiveness." (PMID 35215358, 2022). "Activation of KDR, which promotes endothelial cell mitogenesis and vascular permeability, plays a vital role in the induction of tumor angiogenesis." (PMID 35837087, 2022). "Smooth muscle actin 2 (ACTA2) and tyrosine kinase growth factor receptor (KDR) were identified as the hub genes, which were significantly downregulated in the tumor tissue of the two patients who responded to treatment." (PMID 34179721, 2021). "Cucurbitacin E, a compound in herbal extracts, can inhibit tumour angiogenesis by inhibiting vascular endothelial growth factor receptor 2- (KDR/VEGFR2-) mediated Jak-STAT3 and mitogen-activated protein kinase (MAPK) signalling pathways." (PMID 34007289, 2021). "In our study of tumor recurrence, a significant correlation with RFS was observed in gene mutations (ATR, ERBB3, KDR, and MUC6) and fusions (GOPC-ROS1 and NTRK1-SH2D2A)." (PMID 34599262, 2021). "Like VEGF, high-affinity VEGF receptor Flk-1/KDR (VEGFR-2) also plays a key role in tumor angiogenesis." (PMID 33790740, 2021). "VEGFR-1 and KDR are mostly distributed on the surface of tumor blood vessel endothelium and regulate the generation of tumor blood vessels." (PMID 33330483, 2020). "Suggestively, we found that the endothelial-related genes CDH5 and KDR appeared as significant poor prognosis factors in these neoplasias." (PMID 32230715, 2020). "IL-6 promotes angiogenesis via MMP-9 activation which induces release of VEGF from cultured ECs and tumor cells and also induces expression of VEGF-R2 (KDR) on cultured ECs." (PMID 33109684, 2020). "This includes two tumors with two mutations: one tumor with both FLT1 and KDR mutations and one tumor with both TEK (TIE2) and KDR (VEGFR2) mutations." (PMID 33322802, 2020). "It is notable that inhibition of KDR alleviates hypoxia and remodels the immunosuppressive tumor microenvironment." (PMID 32855362, 2020). "Kinase insert domain receptor (KDR, also known as vascular endothelial growth factor receptor 2) is the main mediator of VEGF signaling that promotes tumor angiogenesis." (PMID 32825052, 2020). "KDR encodes VEGFR-2, the key receptor mediating endothelial cell proliferation and sprouting, leading to angiogenesis and tumour promotion upon binding and signalling through the VEGFA pathway." (PMID 33353148, 2020). "Bevacizumab inhibits VEGF to bind its receptor flt-1 and KDR on endothelial cells to reduce tumor angiogenesis and tumor growth by inactivating VEGF." (PMID 31598150, 2019). "Plumbagin, an active compound of this plant, exerts an anti-angiogenesis effect by downregulating the PI3K/Akt, VEGF/KDR, and angiopoietins/Tie2 pathways and factors related with cancer angiogenesis and tumor cells, including bFGF, ET-1, CTFG, and VEGFB." (PMID 30871059, 2019). "Other variants detected in this tumor, such as those inFGFR3,PDGFRA,KDR (c.1416A>T),CSF1R,EGFR,RET,HRAS,PIK3CA,FLT3 (c.1310-3T>C), andSMAD4, are benign." (PMID 32612806, 2019). "Based on logFC and Betweenness Centrality index values for network nodes, tumor VM formation-related genes, namely, KDR, FLT1, and CDH5, were revealed to be important upregulated hub genes." (PMID 30674871, 2019). "IGF-1 and KDR are involved in promoting tumoral cell growth, neoplastic transformation processes, angiogenesis, cell migration and tumor progression." (PMID 31354524, 2019).
tumor (continued). "Other significant somatic mutations were detected on Chromosome 16; BRAF gene (42% tumors), Chromosome 13; KDR (83% tumors) and Chromosome 20; STK11 with one missense variant detected in 8 of 12 (67%) samples in the matched normal and tumor pairs." (PMID 29854308, 2018). "This concept is indeed substantiated by our finding of abrogation of the VEGFR2/KDR estrogen responsiveness upon siNup153, given the relevance of the VEGF-VEGFR2 signaling in tumor-associated angiogenesis." (PMID 29963256, 2018). "NRP1 and KDR transcripts were detected in a majority of tumors (at least one positive biopsy core per tumor) of both GAC (6/11 and 7/11 tumors for NRP1 and KDR, respectively) and PDAC (9/11 and 8/11 tumors, respectively) in the HPA‐TMA." (PMID 30027561, 2018). "VEGFR-2/KDR is more easily targetable than VEGF because VEGFR-2/KDR is highly expressed on the surface of the activated endothelium in tumor tissues, in contrast to VEGF, which is mainly located in the interstitial space between cells." (PMID 29370209, 2018). "As shown in there was a marked decline in the expression of the VEGF/KDR and Ang2 proteins in the tumor tissues from both the plumbagin and thalidomide treatment groups (P < 0.05)." (PMID 28122355, 2017). "There was not a difference between high-dose plumbagin and thalidomide treatment groups for the tumor VEGF/KDR and ANG2/TIE2 levels." (PMID 28122355, 2017). "KDR directly regulates tumor angiogenesis and its high expression correlated with BC lymph node metastasis." (PMID 28968987, 2017). "The tested mutations are from four genes, including two tumor suppressors (TGFBR1 and CHEK2) and two oncogenes (KDR and ERBB2)." (PMID 28743916, 2017). "Gene mutations in the genes encoding EGFR, FGFR2, KDR, and RET were discovered in the patient's tumor tissue by whole exome sequencing and the patient was treated with a combination of the targeted drugs cetuximab and sunitinib." (PMID 27149458, 2016). "KDR also is an important factor in tumor progression and development due to its pro-angiogenic effects." (PMID 28773588, 2016). "Quantitative real-time polymerase chain reaction confirmed the overexpression of EGFR and KDR genes in the tumor tissue." (PMID 27149458, 2016). "The significantly mutated cancer-related genes that were identified in tumor tissue included EGFR, KDR, FGFR2, and RET." (PMID 27149458, 2016). "Recently, we demonstrated that PTK7 displays phenotypes ranging from oncogenic to tumor-suppressive depending on its concentration relative to those of its binding partners, such as kinase insert domain receptor (KDR)." (PMID 27689325, 2016). "In both A549 and SKMES1 cells, siNP1, siNP2 and KDR blockade alone, significantly inhibited tumor cell proliferation relative to untreated and scrambled controls." (PMID 25889301, 2015). "Examples of such promoters that have been used in targeted gene therapy are E-selectin and endothelial-specific kinase insert domain receptor (KDR/flk-1) which are upregulated in tumor endothelium." (PMID 25606974, 2015). "Ten variants were identified from eight genes in both the tumor and normal groups (APC, EGFR, FGFR3, KDR, MET, PDGFRA, RET and SMO)." (PMID 25404506, 2014). "The immunostain of on tumor showed more significant expression pattern of human KDR on tumor vessels in MT (+) group (0.44±0.077 mm2/0.25 mm2) than in MT (−) groups (0.18±0.017 mm2/0.25 mm2)." (PMID 24804772, 2014). "Even though in different tumor mouse models blocking VEGF or the VEGF receptor 2 (VEGFR2 or KDR) with inhibitors was shown to effectively reduce tumor vasculature or disrupt the existing vasculature, the tumors were more aggressive and invasive." (PMID 25365172, 2014).
tumor (continued). "2.17-mAlb decreased the expression of vascular marker CD31 and the key VEGF receptor KDR that is critical to tumor angiogenesis suggesting that the nanobody suppressed angiogenesis." (PMID 24587106, 2014). "PDGFRA, KIT, and KDR genes that are located on the amplified segment 4 q12 probably play an important role in tumor biology due to their increased expression of receptors and their ligands." (PMID 23537212, 2013). "Knockdown of KDR, PKCα, PLCγ and Raf1 by siRNA significantly attenuated tumour inhibitory effects of brucine." (PMID 23905676, 2013). "A number of preclinical and clinical studies have shown that many small-molecule KDR inhibitors are capable of inhibiting angiogenesis, tumor progression, and dissemination." (PMID 22408460, 2012). "The proliferation rate of the endothelial cells in tumor tissue is 500 times faster than that of the normal endothelial cells, which leads to the higher levels of KDR gene in many human tumor endothelial cells." (PMID 21418659, 2011). "In this study, we proposed that the use of KDR promoter in combination with double suicide genes that were specifically activated in the tumor's vascular endothelial cells would provide us with high levels of tumor specificity." (PMID 21333030, 2011). "Because of its specific expression in the tumor tissues, KDR promoter has been used to express target genes in some tumors." (PMID 21418659, 2011). "Vascular endothelial growth factor A (VEGFR-1) and Flk-1/KDR (VEGFR-2) are key regulators for tumor angiogenesis and tumor growth." (PMID 21808639, 2011). "In contrast, the expression of VEGFA receptor gene (KDR) was significantly higher in EFEMP1c6-derived tumor compared that of U251HF." (PMID 21955618, 2011). "Tumor targeted expression of CDglyTK gene driven by KDR promotor represents a novel strategy for effective gene therapy of tumor with intrinsic KDR." (PMID 21418659, 2011). "Previous studies have shown that the KDR gene is specifically expressed in the vascular endothelial cells and some tumor cells." (PMID 21418659, 2011). "We examined expression of the 3 receptor genes PDGFRA, KIT, and KDR, because of their central function in tumor biology and their significance as therapeutic targets." (PMID 20686603, 2010). "Vascular endothelial growth factor-A and its receptor KDR were expressed in the tumour cells of about half the cases, whereas Flt-1 expression was rarely observed (16%)." (PMID 15841074, 2005). "In general, KDR is recognised as the predominant signal transducer of tumour angiogenesis, whereas Flt-1 (and especially its soluble form) is a negative regulator of VEGF availability." (PMID 15841074, 2005). "For example, it was observed that hsa-mir-3133 and KDR dominate the 4-way relationship between gene, miRNA, protein, and tumor purity, which also implies the 3-way correlation between hsa-mir-3133, KDR, and tumor purity." (PMID 40228208, 2025). "A reported case of recurrent ONB overexpressed both VEGF and KDR in the tumor tissue." (PMID 40710426, 2025). "It targets several receptors implicated in tumor growth and angiogenesis, including KIT, VEGFR2 (KDR), VEGFR3 (FLT4), and FLT3, making it a candidate for treating GISTs, particularly in patients who have developed resistance to standard therapies like imatinib." (PMID 40733131, 2025). "Treatment with ramucirumab, a KDR‐targeting monoclonal antibody, in combination with bevacizumab efficiently reduced tumor growth and angiogenesis in an in vivo xenograft mouse model, suggesting a novel therapeutic strategy for drug‐resistant patients with NSCLC." (PMID 40843133, 2025). "Among these factors, VEGF-A plays a dominant role in tumor angiogenesis, mainly through KDR." (PMID 41415563, 2025). "Notably, in non‐responders, T1 tumor cells were engaged in an interplay with meCAFs via VEGFC–KDR signaling (kinase insert domain receptor; VEGF receptor 2) and exclusively received FGF2–FGFR1 signals from meCAFs." (PMID 40843133, 2025).
tumor (continued). "However, treatment with a neutralizing monoclonal antibody (mAb) against KDR/Flk-1 significantly inhibits bFGF-induced tumor development." (PMID 38672182, 2024). "Notably, PDGFRA and KDR play crucial roles in enhancing metastatic potential, highlighting the complex interplay driving tumor heterogeneity." (PMID 39590338, 2024). "The positive rates of VEGF and KDR were 88% (53/60) and 85% (51/60), respectively, in 60 cases of cholangiocarcinoma tissues, and their expression levels were up-regulated with the increase in the tumor pathological stage and cellular grade." (PMID 38708333, 2024). "KDR is overexpressed in neovascular tumor endothelial cells compared to normal endothelial cells." (PMID 38650036, 2024). "KDR is the human gene encoding VEGF receptor 2, which plays a major role in mediating VEGF-induced responses such as endothelial cell development and the direct regulation of tumor angiogenesis." (PMID 37120792, 2023). "RAMP2+ tumor endothelial cells (TECs) and PROX1+ lymphatic endothelial cells (LECs), were reduced in the PD-1+SMI group and highly expressed VEGF-associated receptor gene KDR (VEGFR1) and FLT1 (VEGFR2) compared with other endothelial subclusters." (PMID 37430270, 2023). "Next, CPL304110 selectivity was analyzed on seven kinases; the results showed that CPL304110 had the highest activity against kinases that share homology with FGFRs (KDR and PDGFRβ) and others that play an important role in tumor development and progression (AURKA, FLT3, IGF1R, JAK2, and TRKA)." (PMID 38282676, 2023). "KDR inhibition may contribute to the moderate anti-tumor efficacy of selpercatinib and pralsetinib in animals bearing Ba/F3 RETG810R allograft tumors, given the lack of target engagement observed." (PMID 37743366, 2023). "To summarise, treatment with ASC-EVs tends to reduce the expression of ITGα5, ITGαV, ITGβ1, ITGβ3, and KDR genes, which could be essential for tumour cell invasion into CAM." (PMID 37174646, 2023). "The vascular endothelial growth factor (VEGF) family, including VEGF; placental growth factor (PLGF); and their receptors Flt-1, sFlt-1, and KDR (also known as VEGFR-1, sVEGFR-1, and VEGFR-2, respectively), are the most important promoters of physiological and tumor angiogenesis." (PMID 35878392, 2022). "Consistent with this phenomenon, we found that VEGFA was highly expressed in malignant/HPC-like cells, while PLVAP+ ECs notably expressed its receptor KDR (VEGFR2), suggesting that these cells may interact within the tumor microenvironment." (PMID 36238304, 2022). "In tumors, endothelial transdifferentiation may be initiated and/or potentiated through the engagement of KDR by elevated VEGF levels in the tumor microenvironment." (PMID 33889304, 2021). "We decided to test whether Cediranib, a potent inhibitor of FLT1/KDR could trigger anti-tumor effect in this Cetuximab-resistant model." (PMID 31936310, 2020). "Therefore, we took the top 20 genes in Degree and the tumor-associated pathway-related gene to take Venn intersection, and identified three Hub genes: PDGFRB, KDR and FGF2." (PMID 32011476, 2020). "This phenotypic correlation with the KDR rs1870377 might support T homozygous findings, hypothetically by promoting tumour vascular density for homozygous carriers." (PMID 33353148, 2020). "Interestingly, in BC ADSCs, the markers CD144, CD146, CD166, and KDR result significantly deregulated suggesting oncogenic alteration also in the tumour microenvironment with a possible role in favouring angiogenesis, tumour cell migration, and proliferation." (PMID 31511776, 2019). "Indeed, HIF-1α stabilization by lactate was associated with increased vascular endothelial growth factor (VEGF) and kinase insert domain receptor (VEGFR2) expression levels by tumor and endothelial cells, respectively." (PMID 30986931, 2019).